MMP2 (matrix metallopeptidase 2)
Diseases named in the same sentence as MMP2 in open-access papers (continued):
Sharing a sentence is not in itself a finding about the gene and the disease.
glioma (continued). "In assays with U87MG glioma cells, which depend upon MT1-MMP for activation of MMP-2, the MT1-MMP-selective N-TIMP-2 variant was uniquely able to reduce the activation of MMP-2 by up to 50%." (PMID 38074088, 2023). "In fact, in organotypical brain slice models, MMP-2 activity was found to be much higher when glioma cells were cultured in the presence of microglia." (PMID 36980765, 2023). "In GBM, CLTX inhibited the invasive growth and metastasis of glioma cells by specifically binding to glioma cell chloride channels and matrix metalloproteinase 2 (MMP2)." (PMID 37190280, 2023). "This was also demonstrated in another study, where VEGF receptor inhibitors impaired the cathepsin B/uPA/MMP-2 pathway and inhibited glioma invasion." (PMID 37398678, 2023). "Subsequently, we explored the effects of DKK1 knockdown and found that it attenuated the vasculogenic networks in glioma cells and decreased the expression levels of metalloproteinases MMP2 and MMP9 and VE-Cadherin." (PMID 37906341, 2023). "Cripto-1 is an oncogenic molecule that promotes the invasion of glioma cells and enhances the expression levels of MMP2 and MMP9." (PMID 37509289, 2023). "SRSF10 upregulates the production of a circular RNA (CIRC-ATXN1) that plays a role in glioma angiogenesis by sequestrating mir-526b-3p, which normally inhibits the expression of pro-angiogenic MMP2 and VEGFA." (PMID 36611187, 2023). "Similar to MMP-9, MMP-2 expression correlates directly with tumor grade and indirectly with survival in glioma." (PMID 37370851, 2023). "ROBO1 knockdown inhibited glioma invasive, migratory, and VM-formation abilities by suppressing the expression of matrix metallopeptidase 2 (MMP2) and matrix metallopeptidase 9 (MMP9)." (PMID 37238655, 2023). "TGF-ß is predominantly released by microglia and promotes glioma cell migration, as well as the release of metalloproteinase 2 (MMP2) which contributes to the degradation of the extracellular matrix and thus supports glioma invasion." (PMID 38275375, 2023). "miR-93-5p inhibits the proliferation, invasion and migration of tumor cells by targeting MMP2 in glioma." (PMID 36896170, 2023). "MMP-2 is specifically upregulated in gliomas as well as in other tumors of neuroectodermal origin such as NB, but not in the CNS." (PMID 37444498, 2023). "Wnt5a enhances glioma cell migration by regulating the expression of MMP-2, which is involved in ECM degradation." (PMID 36675073, 2023). "More recently, a study revealed that IGFBP2 promotes vasculogenic mimicry by modulating CD144 and MMP2 expression in glioma." (PMID 37737709, 2023). "Increased expression of the Fz antagonist sFRP2 was shown to prevent glioma invasion by reducing tyrosine phosphorylation of β-catenin and downregulating matrix metalloprotease-2 (MMP-2)." (PMID 35163279, 2022). "Our study demonstrated that SCIN expression was high and correlated with MMP2/9, a poor prognosis, and immune cell infiltration in gliomas." (PMID 36291348, 2022). "Chlorotoxin purified from Leiurus scorpion, a chloride channel inhibitor, has been identified to suppress glioma cell invasion via binding to MMP-2, and voltage-gated chloride channel were specifically expressed in human astrocytoma and glioma cells." (PMID 36033489, 2022). "The highly expressed MMP-2 proteins on the surface of glioma cells can cleave their specific cleavage sequence (e.g., PLGA) in the linker; thereby, the active CPP–cargo complex specifically penetrates the glioma cells." (PMID 35631493, 2022). "Studies have shown that overexpression of IGFBP2 can increase the malignant degree of glioma and up-regulate the expression of invasion protein MMP2, thereby enhancing the invasion ability of glioma cells." (PMID 36110851, 2022). "Since MMP2 is one of the main proteases involved in the invasive behavior of cells, the inhibition of the activation of MMP2 through MT1-MMP by EGCG determines a reduction in the invasiveness of glioma cells." (PMID 35328780, 2022).
glioma (continued). "Reactive astrocytes aid the parenchymal infiltrative capacity of glioma cells and stimulate their uncontrolled proliferation by expressing matrix metalloproteinase-2 (MMP2) and secreting stromal cell-derived factor-1 (SDF1)." (PMID 35057010, 2022). "To further investigate the potential cause of the association between SCIN expression and the EMT of a glioma, we identified SCIN and MMP2/9 in our clinical tissue samples by IHC and Western blot analysis." (PMID 36291348, 2022). "We observed that SCIN and MMP2/9 protein expressions were upregulated significantly in glioma samples compared with normal brain tissues and progressively increased with the glioma grade." (PMID 36291348, 2022). "miR-4262 expression downregulation inhibits glioma proliferation and migration by suppressing the expression of MMP2 and MMP13, and miR-34a inhibits glioma cell migration by regulating MMP-9." (PMID 36479040, 2022). "In glioma, Sp1 is upregulated and enhances MMP-2-mediated cell invasion, which indicates a decreased survival." (PMID 35276059, 2022). "Some subclasses of MMP and the gelatinase subclass to which MMP2 and MMP9 belong are associated with glioma invasion." (PMID 35448036, 2022). "We used the Kaplan–Meier method and Cox proportional hazards model to assess the impact of SCIN and MMP2/9 on glioma patients’ survival." (PMID 36291348, 2022). "It has been also described that the CCL5/CCR5 axis increased cellular invasiveness via the induction of MMPs, and, more specifically, CCL5 modulated glioma cells’ migratory and invasive activities due to MMP2 upregulation." (PMID 36139013, 2022). "Another group evidenced MMP-2 correlation with glioma and found that expression of MMP-2 was significantly correlated with tumor diameter and grade." (PMID 35884733, 2022). "Slc39a1 is a zinc ion transport protein related to the progression of glioma by promoting MMP2 and MMP9, and is increased in the progression of schizophrenia." (PMID 36614117, 2022). "For example, Wnt-5a enhances the migration of glioma cells by altering the synthesis of MMP-2 through β-catenin-independent signaling; this includes pathways regulating planar cell polarity and calcium dynamics." (PMID 35163279, 2022). "RYK knockdown in glioma cells suppressed matrix metalloproteinase-2 (MMP2) and Wnt5a-induced invasion, suggesting RYK can regulate extracellular matrix degradation and tumor invasive capacity." (PMID 35204808, 2022). "In this study, SCIN was significantly associated with a poor prognosis, tumor immune infiltrates, and MMP2/9 expressions in a glioma." (PMID 36291348, 2022). "Increased intracellular calcium levels and p-CaMKII lead to upregulated expression of calcium-dependent MMP2 in glioma cells (Molecular event 29); MMP2 has been previously associated with GBM cell migration and invasion." (PMID 36555253, 2022). "Among MMPs, MMP2 has been shown to mediate migration aninvasion in gliomas through focal adhesion kinase (FAK) and Janus kinase (JAK)-signal transducer and activator of transcription (STAT) signaling." (PMID 36184634, 2022). "TLR2 promotes GAM production of MMP14, which is essential for MMP2 release and glioma invasion, and microglial expression of MT-MMP, which cleaves proMMP2 into its active form, leading to tumor invasion." (PMID 35448036, 2022). "Clinicopathological analyses revealed that an elevated expression of SCIN in glioma patients was linked to an increased WHO grade and a poor survival, moreover, SCIN expression was positively correlated with MMP2 and MMP9 expressions." (PMID 36291348, 2022). "Specially, a significant increase in MMP2 expression corresponding to glioma malignancy grade with the highest peak in glioblastoma." (PMID 35280742, 2022). "Current research has shown that glioma cells frequently activate the perk arm of the UPR by increasing the levels of the metalloproteinases (MMPs) MMP2 and MMP7, which promote the epithelial-mesenchymal transition (EMT)." (PMID 36727065, 2022).
glioma (continued). "Smaller diameter gliomas unveil lower MMP-2 expression, while in larger diameter malignant gliomas MMP-2 is highly expressed, with corresponding reduction in the expression of tissue inhibitory proteins and tissue inhibitors of metalloproteinases (TIMPs)." (PMID 35328780, 2022). "The result indicated that overexpressed CBX7 and downregulated CBX8 in glioma cells showed a decreased expression of MMP2 and MMP9 and displayed significantly lower invasion abilities in scratch wound-healing assay when compared to the control." (PMID 36034290, 2022). "The expression of MMP-2 in glioma has been reported to be an important key molecule involved in malignancy and invasion." (PMID 35204054, 2022). "The Kaplan–Meier survival analysis of our clinical samples showed that an overexpression of SCIN, MMP2, and MMP9 were associated with a poor prognosis of glioma patients, respectively." (PMID 36291348, 2022). "Their study demonstrated that CCR7 mediates TGFB1-induced migration of glioma cells through the activation of matrix metalloproteinase 2 (MMP2)/9." (PMID 34643804, 2022). "Studies have shown that TGF- β can promote the metastasis of glioma by upregulating synthesis and matrix metalloproteinase-2 (MMP-2), and downregulating metalloproteinase-2 (TIMP-2)." (PMID 36506566, 2022). "SERPINE2 is a protein that is secreted into the extracellular matrix, and it inhibits cell invasion in PCa and glioma, which is related to the inhibition of uPA, MMP-2, and MMP-9 activities." (PMID 36142828, 2022). "IL33 has been found to activate NFkB-transcription of MMP2 and 9 initiating migration and invasion of glioma cell lines U251 and U87 as assayed by using transwell chambers." (PMID 33805316, 2021). "Studies have found that miR-21 can target reversion-inducing cysteine-rich protein with kazal motifs (RECK) to regulate glioma cell invasion and the expression of MMP2/9." (PMID 34425834, 2021). "Recombinant ANG-2 in glioma cell lines activated MMP-2 expression in tumor cells and promoted invasiveness, leading to the conclusion that ANG-2 plays a critical role in tumor cell infiltration by activating MMP-2." (PMID 34439141, 2021). "Cy5.5 fluorescein conjugated to the C6 peptide was taken up by MMP-2 expressing glioma cells in vitro and homed to both intratibial PC-3 prostate xenografts and orthotopic U87 glioma xenografts in vivo." (PMID 33918106, 2021). "In fact, the truth that the low the miR-361-5p expression, the high the tumor grade has been discovered in gliomas, and increasing miR-361-5p level can limit cellular migration and invasion, as well as abate MMP-2 expression." (PMID 34321465, 2021). "In glioma, increased EFEMP1expression promotes tumor invasion and progression by modulating the extracellular matrix by increasing the expression of MMP2, MMP9 and ADAMTS-5 via Notch signaling." (PMID 34204134, 2021). "MMP2 have been identified as an essential factor in the switch to the angiogenic phenotype in some tumors such as chondrosarcoma and glioma." (PMID 34972532, 2021). "RT-qPCR and Western bot suggested that MMP-2 level in gliomas cells was suppressed by miR-361-5p mimic while enhanced by miR-361-5p inhibitor." (PMID 34321465, 2021). "Overexpression of a miR-10b-5p mimic in glioma cells increased motility by upregulating RhoC (a regulator of focal adhesion assembly) and MMP2; all these effects were reversed by an inhibitor of miR-10b-5p." (PMID 34769339, 2021). "An increased amount of p-JNK, p-c-Jun, integrins, and MMP-2 was detected in PP-OE glioma cells compared with the Ctrl cells." (PMID 34480020, 2021). "TLR2 upregulates membrane type 1 matrix metalloprotease (MT1-MMP) and metallopeptidase 14 (MMP14) in MG to activate glioma-sourced MMP2 when responding to TLR2 endogenous ligands and thereby facilitate glioma invasion." (PMID 34671362, 2021).
glioma (continued). "For instance, Ang-2, which functions as a context-dependent Tie2 agonist, is overexpressed in gliomas, where it can promote invasion through activation of matrix metalloprotease 2 (MMP2)." (PMID 33673213, 2021). "The overexpression of MMP-2 and MMP-9 was associated with various tumor progressions, including rectal cancer, glioma, and papillary thyroid carcinoma." (PMID 33959183, 2021). "TLR2 promotes TAM production of MMP14, which is essential for MMP2 release and glioma invasion, and the microglial expression of the metalloprotease MT1-MMP, which cleaves the pro-MMP2 into its active form, resulting in tumor invasion." (PMID 33766119, 2021). "MMPs including MMP-2, which degrade extracellular matrix to overcome the extracellular matrix barrier at the invasive fronts of tumors, promote invasion of glioma cells into adjacent brain structures." (PMID 34480020, 2021). "The U251N glioma cell line showed more substantial transmigration through a Boyden invasion chamber when co-cultured with astrocytes due to secreted MMP2." (PMID 33805316, 2021). "Collectively, these data suggest that fraxetin had an inhibitory effect on the migration and invasion of glioma cells via downregulating MMP-2 and MMP-9." (PMID 33959183, 2021). "Several studies have indicated that MMP2 promotes the migration and invasion of glioma cells, lung cancer cells, and RA-FLSs." (PMID 33692802, 2021). "Many studies have reported that high levels of TGF-β, EGF, MMP-2, MMP-9 and IL-10, and low levels of IL-12 can be produced by M2 polarized glioma-associated microglia/macrophages to promotes invasion, proliferation, immune evasion and angiogenesis of glioma." (PMID 34446611, 2021). "Meanwhile, miR-361-5p stands for a repressor for matrix metalloproteinase (MMP)-2 transcription in gliomas migration and invasion." (PMID 34321465, 2021). "In this study, we found out that fraxetin inhibits the invasion and migration of glioma by downregulating the expression of MMP-2 and MMP-9 in a dose-dependent manner." (PMID 33959183, 2021). "Yao validated that circDYM abated depressive disorder by sponging miR-9 to regulate microglial activation, and circATXN1 can regulate glioma angiogenesis via the miR-526b-3p/MMP2 pathway." (PMID 34717547, 2021). "Treatment of human glioma cells with plumbagin, a herbal naphthoquinone, inhibited cell migration via downregulating MMP-2/-9 expression and the PI3K/Akt signaling pathway." (PMID 34439380, 2021). "Taken together, the results suggest that NE increases the expression of CD147 by activating the ERK signalling pathway in glioma cells and then induces the expression of MMP‐2 and MMP‐9 to promote tumour invasion." (PMID 34169637, 2021). "Specifically, high levels of MMP-2/9 expression are observed in the process of glioma development and tumor cell invasion." (PMID 34530814, 2021). "On the other hand, in glioma, DDR1a is able to induce invasion, adhesion, and MMP2 activation and, in NSCLC, DDR1a has a stronger effect in cell migration and invasion than DDR1b." (PMID 33917302, 2021). "MMP2, MMP9, and VE-cadherin are classic proteins associated with VM formation in glioma cells, and their high expressions suggest enhanced VM formation ability." (PMID 33542193, 2021). "Further studies are needed to reveal substrates of c-Cbl and how c-Cbl promotes glioma invasion through upregulating MMP2 expression." (PMID 33466790, 2021). "FoxM1 directly regulates the expression of MMP-2 at the transcriptional level to promote glioma progression." (PMID 32429421, 2020). "Another study links ClTx to the matrix metalloproteinase 2 (MMP-2), which is involved in tumor invasion and is overexpressed in glioma." (PMID 32429050, 2020). "PEG-INOPs-AF680/CTX reduced the expression of matrix metalloproteinase 2 (MMP-2) by 40% in glioma cell surface, which is an essential component in the glioma cell invasion pathway." (PMID 32722002, 2020).
glioma (continued). "High expression of CD147 promoted the secretion of MMP-2 and the increment of lactic acid, which accelerated the augmented invasion and metastasis of glioma induced by psychological stress." (PMID 33178600, 2020). "Our study is the first to demonstrate that Porf-2 is underexpressed both in glioma and neuroblastoma, and also that the overexpression of Porf-2 suppresses cell migration through the MMP-2/9 signaling pathway." (PMID 32676454, 2020). "A likely candidate would be MMP2, because this gelatinase is activated by most of the MT-MMPs and can enhance the migration of different cell types, such as 3T3 fibroblasts and glioma cells." (PMID 32872536, 2020). "The local administration of THC downregulated the expression of metalloproteinase-2 (MMP-2) in mice bearing glioma tumors." (PMID 32708138, 2020). "The ratio of Bcl2/BAX and expression of MMP2 were increased in glioma cell with the KLHDC8A plasmid." (PMID 32851798, 2020). "To further investigate the effect of psychological stress on the invasion potential of glioma cells, we examined the expression and secretion of MMP-2 and MMP-9." (PMID 33178600, 2020). "Yin also found that norepinephrine increased the secretion of MMP-2 and promoted the migration and invasiveness of glioma T98G cells." (PMID 33178600, 2020). "In conclusion, LINC00339 regulates VM formation by regulating the miR-539-5p/Twist1/MMP-2/MMP-14 pathway in glioma." (PMID 32169087, 2020). "Lactate was shown to promote glioma migration by the TGFβ2-dependent regulation of matrix metalloproteinase-2 (MMP2)." (PMID 31822964, 2020). "In vitro experimental results show that SLC39A1 promotes proliferation of glioma cells, inhibits their apoptosis, and promotes expression of MMP2\MMP9." (PMID 33292262, 2020). "In contrast to many published studies that examined glioma cell lines, we observed that the largest portion of MMP2 in supernatants from primary astrocytes was activated." (PMID 32872536, 2020). "miR-140-5p directly targets VEGFA and suppresses VEGFA/MMP2 signaling to inhibit angiogenesis in colorectal cancer and glioma cells." (PMID 32993787, 2020). "In the meantime, we used a CCK-8, flow cytometer, RT-qPCR, western blot, and other technologies to analyze the correlation between SLC39A1 and glioma proliferation and apoptosis in vitro, and the expression of invasion-related MMP2\MMP9 proteins." (PMID 33292262, 2020). "Glioma cells express high level of MMP2 which is responsible for its aggression and invasion capabilities." (PMID 33473259, 2020). "The complex of MMP14, TIMP2, MMP2 and avß3 integrin leads to localized MMP2 activation and increases glioma cell migration in vitro." (PMID 32872536, 2020). "Several investigations have indicated that the MMP2 gene is a significant marker related to glioma formation." (PMID 32392739, 2020). "Then PCNA, MMP-2 and MMP-9 were costained in U251 and T98G cells with immunofluorescence staining assays, the result further showed that unigene56159 silencing suppressed the MMP-2 expression in glioma cells." (PMID 31789416, 2020). "High expression of CD147 promoted the secretion of MMP-2 and the level of extracellular lactic acid, which accelerated the augmented invasion and metastasis of glioma induced by psychological stress." (PMID 33178600, 2020). "Chlorotoxin (CTX) is a minute 4 kDa protein made up of 36 amino acid residues, commonly known for its binding affinity to chloride channels and matrix metalloproteinase-2 (MMP-2) of glioma tumors of the spine and brain." (PMID 31857956, 2019). "In fact, miR-140-5p was effective to inhibit EMT in esophagus cancer and miR-140-5p also inhibited glioma metastasis via repressing MMP2 expression." (PMID 31762692, 2019). "As our results attribute peritumoral PNN degradation primarily to glioma-released MMPs (MMP-2, MMP-3, and MMP-9), we used a cocktail of these MMPs to degrade PNNs experimentally." (PMID 30413686, 2018).